IFNG (interferon gamma)
Diseases named in the same sentence as IFNG in open-access papers (continued):
Sharing a sentence is not in itself a finding about the gene and the disease.
diabetes (continued). "Diabetes has been linked to elevated levels of plasma TNF, IL-1b, interleukin 6 (IL-6), interferon-g (IFNg), and PAI-1, as well as changes in immune cell responses, resulting in chronic low-grade inflammation." (PMID 40283013, 2025). "Their findings demonstrated hyperexpression of the inflammatory response and suppression of the IFNγ pathways in both the diabetes and the intermittent hyperglycemia groups." (PMID 39594205, 2024). "In a mouse model, those with pre-diabetes had increased lung pathology and lower concentrations of Th1 inflammation (IFNγ, TNFα)." (PMID 39594205, 2024). "Neopterin is a product of interferon-gamma (IFN-γ) activation of macrophages and has been proposed as a serum marker for peripheral neuropathy in diabetes mellitus." (PMID 39409118, 2024). "In the studies presented here, IFNγ levels were increased in both the Ins2Akita/+ and Leprdb/db models at early stages of diabetes." (PMID 37670018, 2023). "As diabetes is linked to cytokine-mediated inflammation leading to loss of functional β-cell mass, we next asked whether treating islets with three key cytokines (TNFα, IFNγ, IL-1β, or a cocktail of all three) affects LIM-domain complex factor expression levels." (PMID 34968409, 2022). "IFNγ participates to diabetes progression by increasing beta cell visibility to immune cells through the upregulation of HLA class I molecules and presentation of beta cell-derived peptides." (PMID 36611907, 2022). "Plasma inflammatory biomarkers, such as interferon-gamma (IFN-γ), have been connected with diabetes development and progression with the use of pro-inflammatory cytokines suggested to measure disease progress." (PMID 34452184, 2021). "Several underlying immune, environmental and host genetic predisposing factors have been associated with TB including diabetes, infection with HIV, malnutrition and deficiency in interferon-gamma (IFN-γ) encoding genes." (PMID 31729564, 2020). "In the current study, IFNγ levels tended to be higher in patients with diabetes (Groups 5 and 6) than in normal individuals (Groups 1 and 2)." (PMID 31504048, 2019). "Fas and IFNγ have been reported to be more important in killing pancreatic beta cells in T-cell dependent murine models of diabetes mellitus although TNFα assistance was essential, as was also confirmed in this model." (PMID 29464051, 2018). "Clearly, many questions still remain as to how IFNγ mediates T cell migration and diabetes in adoptive transfer models." (PMID 30555479, 2018). "Here we use IL-1β and interferon-gamma (IFN-γ) to model the inflammatory milieu in diabetes and show that these cytokines attenuate GSIS and dampen both glucose-sensitivity and coupling efficiency of oxidative phosphorylation." (PMID 29953508, 2018). "In contrast, induction of IFNγ in NOD mice protected against diabetes development by suppressing Th17 activity and inhibiting IL-17 production." (PMID 27790217, 2016). "To further elucidate the role of IFNγ in the development of hyperglycemia, we utilized the same MLD-STZ model to induce diabetes in IFNγ−/− mice." (PMID 27790217, 2016). "This view changed with the demonstration that IFNγ-deficient NOD mice were still susceptible to insulitis and diabetes, albeit with delayed onset." (PMID 27790217, 2016). "Our study also indicated that the treatment of chelerythrine downregulated CD36 and IL-1β as well as inflammation related genes like IFNγ and TNFα, which are of great benefits for the treatment of diabetes." (PMID 26183621, 2015). "In contrast, the proinflammatory background of diabetes, which includes increased placental levels of TNFα, IFNγ, and IL-1β, promotes enhanced CX3CL1 gene expression." (PMID 23956503, 2013). "For example, in NOD mice, which develop diabetes spontaneously, the activation of NK cells with poly I:C protects against diabetes through the secretion of IFNγ." (PMID 22558306, 2012).
diabetes (continued). "Dendritic cells (DCs) from NOD mice produced high levels of IL-12 that induce IFNγ-producing T cells involved in diabetes development." (PMID 21716731, 2011). "The overproduction of IL-12 by NOD APC is thought to contribute significantly to disease development, since it leads to activation of IFNγ-producing T cells which mediate diabetes." (PMID 21716731, 2011). "The effect of diabetes on the expression of various inflammatory (TNFα, IL-6, IL-1β and IFNγ) and apoptosis markers (caspase-1) was also evaluated in intact retinas from wt, ApoE−/−, TNFα−/− and ApoE−/−/TNFα−/− mice." (PMID 20856927, 2010). "In wt mice, diabetes resulted in a clear increase in TNFα, IL-6 and IL-1β mRNA expression levels (p<0.01, p<0.01 and p<0.05, respectively) and in a tendency to higher IFNγ and caspase-1 mRNA levels (n.s.)." (PMID 20856927, 2010). "In the retinas of diabetic wt mice, we also found significantly increased levels of TNFα, IL-6 and IL-1β mRNA expression and a tendency to increased IFNγ and caspase-1 mRNA, indicating some degree of local inflammation after 8 weeks of diabetes." (PMID 20856927, 2010). "Diabetes reprograms T cells and macrophages in the testis, promoting a glycolysis-dependent pro-inflammatory phenotype that secretes interleukin-1β (IL-1β) and interferon-gamma (IFN-γ), thereby exacerbating oxidative stress and apoptosis." (PMID 41445731, 2025). "In those diabetes participants where S‐specific T cells were detected, the response was unfocused, with the expected expression of IFNγ, TNF, and IL‐2, alongside a significant increase in the expression of the Th2 cytokine IL‐13 in S‐specific CD4+ and CD8+ T cells from both diabetes groups." (PMID 41367201, 2025). "While IL-1β, IFNγ and TNFα have all been detected in islet infiltrates from human donors with type 1 diabetes, most of our understanding of their effects and functional pathobiology in diabetes comes from rodent model systems." (PMID 37113489, 2023). "In addition, PAP1 prevented the diabetes-induced repolarization defects through reducing the secretion of the inflammatory cytokines IL-10, IL-12p70, GM-CSF, IFNγ, and TNFα." (PMID 34623540, 2023). "PD-L1 also represents another example of proteins upregulated by IFNγ in alpha and delta cells that might impact diabetes development." (PMID 36611907, 2022). "Here in this study, we found that diabetes likely affected the phenotype of macrophages in such a delicate manner, since diabetes seemed to alter the levels of markers for macrophage functionality, iNOS, TNFα and IFNγ, and the levels of PCNA, a cell proliferation marker." (PMID 36405726, 2022). "In this context, gene products activated by IFNγ in alpha and delta cells might impact diabetes development." (PMID 36611907, 2022). "M(IFNγ) was chosen as the read-out macrophage subpopulation, taking into account that hyperglycemia is able to polarize macrophages towards an M1-like phenotype and the clinical observation of an increased M1/M2 ratio in diabetics." (PMID 35163309, 2022). "Conversely, transgenic mice with beta cell specific IFNγ expression become diabetes prone." (PMID 36611907, 2022). "Indeed, at 50 ng/mL, an up-regulation was only observed for IFNγ in response to the diabetes and CAD marker IL-18, but a reduction for at least one of the three T-cell activity markers in response to all other biomarkers except CX3CL1 and periostin." (PMID 34281240, 2021). "Polymorphisms of genes encoding pro- and anti-inflammatory cytokines (TNFα-308 G/A, IFNγ +874 A/T, IL-10–1082G) may be responsible for nerve damage in neuropathy, which is a common complication of diabetes." (PMID 32751810, 2020). "Furthermore, our results showed that overexpression of Zbtb32 delayed diabetes onset, limited T-cell proliferation, and decreased IFNγ production from autoreactive T cells in an adoptive transfer model of T1D6." (PMID 29707204, 2018).
diabetes (continued). "Together these data suggest that the protection from diabetes seen in mice deficient in IFNγ signaling is not caused by the inability of the islet vasculature to present cognate antigen to autoreactive T cells through MHC class II." (PMID 30555479, 2018). "In addition, transient overexpression of Zbtb32 in islet-specific CD4 T cells delayed diabetes development, and decreased both proliferation and IFNγ production in islet-specific CD4+ T cells." (PMID 29707204, 2018). "It has also been observed that diabetes-prone BioBreeding (BBdp) rats housed in specific germ-free (GF) conditions and weaned onto cereal diets displayed an upregulation of the interferon gamma (Ifng) and interleukin 15 (Il15) genes and a downregulation of the forkhead box P3 (Foxp3) gene." (PMID 25421534, 2014). "IFNγ production by activated NK cells is protective from diabetes." (PMID 22558306, 2012). "In contrast, expression of B7-2 on B cells may be very important for diabetes induction, since B cells have been shown to be crucial for diabetes development and are excellent inducers of IFNγ-producing T cells that respond to pancreatic antigens." (PMID 21716731, 2011). "Intraperitoneal injection of a long-lived noncytolytic murine IL-10/Fc fusion protein into young NOD mice prevents insulitis and diabetes by blocking the production of proinflammatory cytokines and IFNγ, and IL-10-transduced islet-specific CD4+ T-cells prevent diabetes transfer in NOD mice." (PMID 21716731, 2011). "In contrast, the increased IRF8 expression in the spleen of diabetes-prone NOD mice may be the result of a high production of IFNγ which is known to induce IRF8 expression in macrophages and T cells." (PMID 21647406, 2011). "Evidence for local up-regulation of IL-6 and IFNγ in retina in diabetes comes from studies in rats." (PMID 20856927, 2010). "Similarly, our previous study showed that after phytohemagglutinin stimulation, the PBMCs of patients with diabetes expressed lower IFNγ and IL-10 levels; however, they had higher monocyte responsiveness, which is measured based on TNFα/IFNγ and IL-6/IFNγ ratios." (PMID 39062154, 2024). "Moreover, we found that IFNγ levels tended to increase in diabetes with abdominal obesity." (PMID 31504048, 2019). "Both ND and diabetes groups contained similar frequencies of TNF‐ and granzyme B‐producing CD8+ T cells, with IFNγ and IL‐2 production being significantly increased in T1D and T2D compared with ND, respectively." (PMID 41367201, 2025). "In a previous study, SEA was found to induce Th1 cytokines such as interferon gamma (IFN-γ), suggesting that SEA plays an important role in the induction of inflammation in patients with diabetes." (PMID 37110462, 2023). "However, using a CD4+ T cell-mediated adoptive transfer model of autoimmune diabetes we observed that even though diabetes does not develop in Ifnγr2-deficient recipient mice, IFNγ-induced MHC class II on IECs is not important for development of insulitis or diabetes." (PMID 30555479, 2018). "In diabetics, the systemic levels of LTB4, TNF-α, IL-6, IL-10, IL-12 and IFNγ were increased as well as the frequency of pro-inflammatory monocytes (CD11b+Ly6ChighLy6G−) compared to healthy mice." (PMID 30242286, 2018). "Furthermore, it should be noted that it is possible that diabetes resistance in IL-21R-deficient NOD mice may be attributed to still unidentified protective alleles in the C57BL/6 genome, as has been identified in disease-resistant IFNγ knockout NOD mice." (PMID 18773086, 2008). "The current results are consistent with empagliflozin modulating levels of inflammatory molecules and may potentially lower inflammation in diabetes by decreasing glucose uptake into CD4+ T cells, resulting in e.g. decreased IFNγ release from the cells." (PMID 40599791, 2025). "IFNγ levels are increased in serum, tears, and the vitreous and aqueous humours of individuals with diabetes with retinopathy, but not in those with diabetes without retinopathy." (PMID 37670018, 2023).
diabetes (continued). "Levels of IFNγ are increased in individuals with diabetes with diabetic retinopathy, but not in those with diabetes without diabetic retinopathy, and are increased in both type 1 and type 2 diabetes." (PMID 37670018, 2023). "Neither interleukin 10 nor interferon gamma were significantly related to diabetes mellitus duration (P. value = 0.267 and 0.298, respectively." (PMID 36443718, 2022). "Interestingly, an increase in IFNγ+ CD4 T cells was seen only in Vancomycin-treated group and not in Neomycin-treated group, despite both groups exhibiting accelerated diabetes to similar degrees." (PMID 36059452, 2022). "It seems that diabetic patients diagnosed with SARS-CoV-2 infection had higher values of IL-2, IL-6, IL-10, and interferon gamma than those without diabetes mellitus (NDM) or impaired fasting glucose (IFG)." (PMID 34201473, 2021). "We have also investigated whether IFNγ promotes upregulation of MHC class II on IECs in vitro, and examined MHC class II expression on IECs during progression to diabetes in NOD mice." (PMID 30555479, 2018). "IFNγ must be acting on a non-immune cell, and the EC is the best candidate, because beta cell specific abrogation of the IFNγR does not prevent diabetes." (PMID 30555479, 2018). "Th17 cells-induced diabetes is inhibited by adding anti-IFNγ antibodies, but not anti-IL-17 antibodies in a mouse diabetes model." (PMID 28698517, 2017). "The absence of a gut microbiota in NOD mice did not affect the overall diabetes incidence but resulted in increased insulitis and levels of interferon gamma and interleukin 12; these changes were counterbalanced by improved peripheral glucose metabolism." (PMID 25390735, 2014). "In insulin dependent diabetes mellitus (IDDM) various agents like interleukin-1 beta, interferon gamma, tumor necrosis factor alpha, alloxan and streptozotocin - could operate by forming free radicals that could attack the mitochondrial genome." (PMID 24250450, 2012). "Previous reports in the NOD model of diabetes have shown that the administration of the probiotic formulation VSL3 decreased the incidence of T1D through IL10 immunomodulation and induction of pro-inflammatory cytokine IFNγ." (PMID 20463897, 2010). "TNF-α and IL-1β have often been mentioned as playing a key role in both type 1 and type 2 diabetes, and IFNγ is another proinflammatory factor that is critical to the pathogenesis of both types of diabetes, but has not been extensively studied in diabetic retinopathy." (PMID 37670018, 2023). "In the present study, we observed that the synbiotic combination decreased the key cytokine IL-6 among other proinflammatory markers (IL-8, IL17a and IFNγ) after only 30 days of treatment in healthy middle-aged volunteers without any suspicion of type 2 diabetes mellitus and cardiovascular diseases." (PMID 33514774, 2021). "Responses to whole killed B. pseudomallei were measured in peripheral blood mononuclear cells (PBMC) by interferon-gamma (IFN-γ) ELIspot assay and flow cytometry and compared to those of control subjects in the region with diabetes (n = 45) and without diabetes (n = 43)." (PMID 26495852, 2015). "Our results indicate that susceptibility to NODAT might be monitored by genotyping KTRs who developed diabetes compared with KTRs who did not develop diabetes for selected major Th 1(IFNG)/ Th-2 (IL-4)/TGFB, T-reg in addition to IL-6, macrophage derived cytokines." (PMID 33727573, 2021). "Treating human islets with GDF15 prevented the apoptosis induced by IL-1β and IFNγ, and administration of GDF15 to non-obese diabetic (NOD) mice prevented the development of diabetes." (PMID 37761001, 2023).
lupus (314 papers, 2006 to 2026). "IFNγ levels are increased in mouse models of lupus, and these levels are associated with the development of autoantibodies and with disease progression." (PMID 40943602, 2025). "In vitro activated splenocytes from miR-182−/−B6/lpr mice and miR-183C−/−B6/lpr mice showed reduced ability to produce lupus-associated IFNγ." (PMID 35873462, 2022). "Together, our data suggested that miR-183C acts through Foxo1 to regulate the production of inflammatory cytokine IFNγ, a key pathogenic cytokine in the lpr lupus model." (PMID 35873462, 2022). "Elevated expression of IFNGR1 and subsequent IFNγ signaling activation promotes the loss of self-tolerance and production of autoantibodies in murine lupus models." (PMID 36199584, 2022). "On the other hand, spontaneous GCs can also originate from defects in T cells, such as the pathogenic accumulation of Tfh cells induced by IFNγ excess in the sanroque lupus model or aberrant production of IL-17." (PMID 36359789, 2022). "Lastly, arthritis in patients with SLE was shown to be associated with IFNγ signatures, which is in contrast to lupus skin involvement, whereby its pathological association is with type I IFN signature." (PMID 35269647, 2022). "Given the known association between type I IFNs and lupus, several recent studies compared the effects of IFNα and IFNγ." (PMID 33519824, 2020). "Heightened Th1 cytokine IFNγ expression has been identified in both human and murine lupus and implicated in lupus pathogenesis." (PMID 32646370, 2020). "In line with observations in mir155-deficient non-lupus animals, we observed a reduction of activated Teffector cells with lower Th17 frequencies and a trend toward lower IFNγ-producing Th1 cells in mir155-deficient PIL-/- mice compared to PIL+/+ animals." (PMID 28719617, 2017). "Lupus pathogenesis is closely associated with interferon gamma (IFN-γ), which plays a central role in innate and adaptive immunity." (PMID 28841837, 2017). "We reported here that deliberate inhibition of selected DLK1-Dio3 miRNAs such as miR-154, miR-379, and miR-300 significantly reduced the production of lupus-associated cytokines IFNγ, IL-1β, IL-6, and/or IL-10." (PMID 27070142, 2016). "SNP rs2069718, located in the intron of IFNG, was associated with susceptibility to systemic lupus erythematosus in a recessive genetic model." (PMID 26063326, 2015). "Moreover, IPA identified other upstream activators likely critical in the cSiO2-triggered Type 1 IFN (IFNAR, IRF-7, and IFNα) and Type 2 IFN (IFNγ) responses observed here and known to be associated with human lupus." (PMID 38361937, 2024). "This suggests that IFNγ may be involved in the initial loss of B cell tolerance early in the development of lupus." (PMID 33519824, 2020). "Type-II IFN (IFNγ) has been implicated in both human and mouse lupus." (PMID 31354738, 2019). "IFNγ and IL-10 expression was reduced in the spleen in the presence of T. gondii, suggesting the suppression of T helper 1 (Th1) and Th2 responses, respectively, both demonstrated to be pathogenic in murine lupus." (PMID 26648937, 2015). "In addition, Tregs have been implicated in preventing the onset of autoimmune and auto-inflammatory conditions associated with aberrant IFNγ signaling such as type 1 diabetes, lupus, and lipopolysaccharide (LPS) mediated endotoxemia." (PMID 24391643, 2013). "Association of IFNG gene polymorphism with systemic lupus erythematosus has also been described in Korean population and polymorphisms in the IFNG/IL-6 gene region may contribute to sex bias in susceptibility to RA." (PMID 23077565, 2012). "Thus, IFNγ excess may result in Tfh cell accumulation, mutation of IFNγ may promote lupus development, and targeting IFNγ may be a potential for SLE." (PMID 38164134, 2023). "Increased interferon-gamma signaling causes excessive T follicular helper development and germinal center formation in some mouse models, and a similar mechanism may operate in OS-exposed lupus patients." (PMID 36148466, 2022).